LEPR (leptin receptor)
Diseases named in the same sentence as LEPR in open-access papers (continued):
Sharing a sentence is not in itself a finding about the gene and the disease.
Obesity (continued). "Thus, the dysregulation of leptin actions, e.g., changes in leptin receptor expression in adipose tissue, may influence obesity and other metabolic disorders development, such as insulin resistance and type II diabetes." (PMID 24243000, 2014). "Given the common pathogenesis between obesity, diabetes, COPD and cancer, and the individual carcinogenesis role of cigarette smoking and leptin gene family, we inferred a possible role of the interaction between smoking and LEPR polymorphism in colorectal cancer susceptibility." (PMID 23593308, 2013). "In addition to regulating hepatic triglyceride in response to modest changes in dietary fat, Gcn2 deficiency profoundly impacts the severity of the obese-diabetic phenotype of the leptin receptor mutant (db/db) mouse, by reducing hepatic steatosis and obesity but exacerbating the diabetic phenotype." (PMID 24130751, 2013). "Leptin receptor polymorphism (LEPR Gln Arg polymorphism) may influence the response to the exposition to cranial radiotherapy and, thus, the individual susceptibility to obesity." (PMID 22284631, 2012). "Notably, obesity in the F line is independent of leptin, the leptin receptor and other characterised single gene obesity mutations relating to central control of appetite or energy balance." (PMID 21915269, 2011). "Other genes such as MC4R, leptin and leptin receptor, Ghrelin (GHRL), peroxisome proliferator-activated receptor gamma (PPARG), oxytocin receptor (OXTR), prohormone convertase-1 and proopiomelanocortin have been implicated in human obesity and will be discussed elsewhere in this journal issue." (PMID 22043167, 2011). "Hence, the study focused to explore the association of leptin receptor polymorphisms (K109R, Q223R and K656N) with obesity and type 2 diabetes in both diabetic and non-diabetic subjects recruited from the local population of Coimbatore." (PMID 21031055, 2010). "For example, the ob/ob [obese], db/db [diabetes] and the Zucker diabetic fatty rat (ZDF) have mutations either in the leptin gene (ob/ob) or in the leptin receptor (db/db) which causes over-eating obesity, unlike the natural history of the disease in humans where leptin is seldom implicated." (PMID 20398338, 2010). "This contrasts with homozygous/bi-allelic carriers of LoF mutations in other genes in the leptin-melanocortin signalling pathway -LEP, LEPR, POMC, PCSK1 and MC4R-who almost inevitably develop severe obesity at an early age." (PMID 41386534, 2026). "Genes downregulated in SHBG-stimulated adipocytes included LEP, LEPR, FLST3, CRTC2, and ID3, all of which are known to contribute to obesity-induced inflammation and insulin resistance." (PMID 40532849, 2025). "In contrast, chronic inhibition of ArcGABA non-LepR neurons effectively prevented and reversed DIO, suggesting a potential anti-obesity treatment strategy." (PMID 40540394, 2025). "On the one hand, hyperphagia, obesity, and hyperglycemia were reported following acute, CRISPR-mediated leptin receptor deletion specifically from AgRP neurons in adult mice." (PMID 40371641, 2025). "In addition, setmelanotide is pioneering a personalized medicine approach to obesity, specifically targeting very rare genetic disorders such as pro-opiomelanocortin (POMC) deficiency, proprotein convertase subtilisin/kexin type 1 (PCSK1) deficiency, and leptin receptor deficiency." (PMID 40016558, 2025). "GLP-1RAs combined with adipokine-targetingagents (e.g., leptin receptor agonists) may achieve more pronounced cardiacfunctional improvement through dual mechanisms involving central appetiteregulation and peripheral lipid metabolism in patients with obesity-relatedcardiomyopathy." (PMID 40927090, 2025). "Genetic variation at the LEPR locus has been suggested to play a significant role in T2DM and obesity." (PMID 40551902, 2025).
Obesity (continued). "Notably, caloric restriction-induced weight loss did not restore the leptin effect and may only serve to enhance the amylin effect, with the diminished response perhaps reflecting chronic leptin receptor desensitization or altered hypothalamic signaling pathways after a state of extreme obesity." (PMID 40192745, 2025). "Obesity-related GERD patients commonly exhibit elevated leptin levels and leptin receptor (ObR) downregulation, a state of leptin resistance." (PMID 41384250, 2025). "This study investigates the relationship between six obesity-related genes (CLOCK, FTO, GHRL, LEP, LEPR, MC4R) and their impact on BMI, WC, HC, WHR, and emotional eating behavior in 220 Romanian adults." (PMID 39203789, 2024). "We calculated the Hardy-Weinberg Equilibrium (HWE) for six genes (CLOCK, GHRL, FTO, LEP, LEPR, MC4R) related to obesity, using genotype frequencies from our dataset." (PMID 39203789, 2024). "Additionally, obesity may increase the levels of soluble LEPR, which limits leptin bioavailability." (PMID 39317805, 2024). "However, treatments aimed at reducing elevated leptin levels, such as Metreleptin, leptin-sensitising medications, soluble leptin receptors, and leptin receptor antagonists, may complement efforts to raise adiponectin levels in the treatment of obesity-related diseases." (PMID 38339282, 2024). "Regarding CLOCK/CT, FTO/AT, GHRL/GT, LEP/GA, LEPR/AG, MC4R/CT we found intermediates values for weight, BMI, waist circumference, and WHR, reflecting moderate levels of body fat and obesity." (PMID 39203789, 2024). "Thanks to research on monogenic forms of obesity, derangements in the central nervous system (CNS) pathways have been recognized, especially regarding changes in leptin (LEP) and its receptor (LEPR)." (PMID 38654832, 2024). "Since CD4+ T cell metabolism has been previously shown to be altered in obesity, we sought to characterize the metabolic phenotype of CD4+ T cells from T cell-specific leptin receptor knockout mice versus littermate control mice on either NC or HFD." (PMID 37276236, 2023). "Polymorphisms in the LEP and LEPR genes are increasingly being studied in conjunction with LEP levels, to provide insight into their roles in obesity-mediated cancers, although data directly linking LEP and LEPR genetic variations to CRC are limited." (PMID 37282602, 2023). "Treatment with leptin downregulates these miRNAs, and hipotalamic silencing of miR-200a increases expression of LEPR and ISR-2 (insulin receptor substrate 2), suggesting that this miRNA can be a target for obesity treatment." (PMID 37375898, 2023). "Among the measurement of the obesity and diabetes genes, the expression level of FTO, CPT1A, LEPR, and LAMIN were significantly downregulated in the intervention group after intervention with green cardamom (P < 0.001)." (PMID 36522620, 2022). "In conclusion, our results demonstrate the difficulty in conclusively explaining human obesity in terms of the well-known LEP and LEPR genes." (PMID 35886710, 2022). "As obesity develops, the increased locally released leptin levels from MAT stimulate mesenchymal stem cells (MSCs), acting through the leptin receptor (LepR) to inhibit osteogenesis and promote adipogenesis." (PMID 35011721, 2022). "This study demonstrated that a green cardamom intervention improved anthropometric indices, glycemic indices, and sexual hormones, as well as the expression level of obesity and diabetes genes FTO, CPT1A, LEPR, LAMIN, and PPAR-γ genes in PCOS women." (PMID 36522620, 2022). "The levels of leptin receptor and p-ERK were significantly higher in the maternal obesity group than in the control group (both p < 0.05)." (PMID 35327669, 2022). "Obesity is a conspicuous trait of the Ossabaw pig and heterozygosity of POMC, LEP and LEPR genes were reported to impact the obesity of humans and mice." (PMID 34585119, 2021). "Onset of overweight or of obesity in LEP and LEPR wt/- was reported to occur during adulthood in previous studies." (PMID 34448070, 2021).
Obesity (continued). "It is pertinent to note that out of the total 10 obesity related SNPs from FTO, ADIPOQ and LEPR genes considered in this study, seven were involved in pair-wise interactions and associated with either risk or protective nature towards manifestation of T2DM." (PMID 34784930, 2021). "Previously, promoter methylation of obesity-related genes including LEP, NPY, and LEPR was involved in tumorigenesis of renal cell carcinoma, and LEPR methylation was associated with prognosis, and predicted renal cell carcinoma recurrence." (PMID 33485366, 2021). "In addition, functional LepR was specifically down-regulated in the hypothalamus of infected obese mice, suggesting that CDV infection in the brain induced leptin resistance in the hypothalamus, which led to obesity, thereby increasing the risk of MetS-associated cognitive impairment." (PMID 34795562, 2021). "The mice with leptin receptor gene knockout (db/db mice) has been extensively used for studying the pathogenesis of T2DM, obesity, leptin signaling, and the interactions among the three." (PMID 32024487, 2020). "These new findings, in conjunction with prior studies demonstrating that leptin drives obesity-mediated breast tumor progression, provided rationale for analyzing the relationship between FGFR1 mRNA and the leptin receptor (LepR) mRNA in breast cancer." (PMID 33019728, 2020). "Obesity was induced either by high‐fat diet (diet‐induced obesity, DIO, with ad libitum chow‐fed controls) or by genetic means in leptin receptor knockout (db/db) mice." (PMID 30907060, 2019). "Other than known syndromes associated with obesity, there are multiple monogenic forms of obesity which include LEP, LEPR, MC4R, and POMC1 majorly." (PMID 31070016, 2019). "Six novel variants were identified in five candidate genes in seven out of 105 children with severe obesity; two in SIM1 (p.W306C and p.Q36X), one in POMC (p.Y160H), one in PCSK1 (p.W130G fs Ter8), two in MC4R (p.D126E) and one in LEPR (p.Q4H)." (PMID 30991789, 2019). "In this study, we evaluated the effect of UC-MSCs on NAFLD in db/db mice that spontaneously develop hyperphagia-induced obesity, T2DM, and NAFLD due to dysfunction of the leptin receptor." (PMID 31781248, 2019). "Some of the monogenic obesity genes which manifest as severe obesity in children are leptin (LEP), leptin receptor (LEPR), pro-opiomelanocortin (POMC), and prohormone convertase 1 (PCSK1)." (PMID 28924523, 2017). "Our results indicate a possible contribution of CNVs in LEPR, NEGR1, ARHGEF4, and CPXCR1 and the intergenic regions 12q15c, 15q21.1a, and 22q11.21d to the development of obesity, particularly abdominal obesity in Mexican children." (PMID 28428959, 2017). "Knock-out of NOS1 in leptin receptor- and NOS1-expressing hypothalamic neurons results in hyperphagic obesity, decreased energy expenditure, and hyperglycemia in mice." (PMID 28396702, 2017). "Thus, individuals with LEPR-positive cancers could be particularly susceptible to high leptin levels seen in obesity irrespective of LEP expression in the tumor itself." (PMID 29212170, 2017). "Human obesity is due to a complex interaction among environmental, behavioral, developmental and genetic factors, including the interaction of leptin (LEP) and leptin receptor (LEPR)." (PMID 28096764, 2016). "Regardless of whether obesity in mice is caused by leptin receptor deficiency (db/db) or high fat diet (HFD – 60% kcal from fat), the loss of skin γδ T cells in obesity results in a reduction in keratinocyte number in the basal layer due to premature keratinocyte differentiation and proliferation." (PMID 27303404, 2016). "Hence, we hypothesised that polymorphisms in LEP and LEPR could lead to an increased risk for differentiated thyroid cancer (DTC), thus establishing the link between the observed epidemiological increases in both thyroid cancer and obesity rates." (PMID 25810718, 2015).
Obesity (continued). "So far, several genes, such as proopiomelanocortin (POMC), leptin receptor (LEPR), leptin (LEP), proconvertase 1 (PC1), and melanocortin 4 receptor (MC4R), have been confirmed as the casual genes to the onset of monogenic obesity." (PMID 24707501, 2014). "Subsequently, it has been reported that BBS proteins are required for leptin receptor (LepR) signaling using a BBS knockout mouse models which reproduce the major features of the human phenotype including obesity." (PMID 22927860, 2012). "Subsequently, it has been found that BBS proteins were required for LepR signaling in the hypothalamus, by using a BBS knockout mouse model which reproduce the major features of the human phenotype, including obesity." (PMID 22927860, 2012). "Our stratified analyses in CoLaus data suggest that sex could potentially modify the association of LEPR variants with obesity-related phenotypes, which is not surprising considering the major differences in both leptin levels and fat distribution between the sexes." (PMID 22028824, 2011). "Moreover, swiftly eliminating LepR from AgRP neurons induces obesity, whereas inhibiting GABAA receptors in the DMH can reverse this obesity phenotype." (PMID 40130157, 2025). "Because we selectively targeted Arc non-LepR neurons in our obesity model, we reasoned that the function of LepR neurons should remain intact and, therefore, leptin action should be maintained." (PMID 40540394, 2025). "Notably, rare, pathogenic mutations in all the genes involved in leptin driven melanocortin pathway (LEP, LEPR, POMC, PCSK1, MC4R, primarily) lead to severe early-onset obesity accompanied by eating disorders." (PMID 39237720, 2025). "In the case of DIO, as our data suggest that HFD feeding increased the activity of Arc non-LepR neurons, leptin, although at an increased level, may not be able to exert a direct inhibitory action on non-LepR neurons and therefore fails to reduce obesity in DIO, causing phenotypic leptin resistance." (PMID 40540394, 2025). "In NPY-GFP::LIC::Ai9 reporter mice, we observed a subset of AgRP neurons that was LepR negative, suggesting a potential role of this subset in promoting obesity." (PMID 40540394, 2025). "It is important to stress that this leptin resistance in DIO mice is only partial, as obesity in these mice is much less severe than obesity in db/db mice completely lacking leptin receptor." (PMID 38165042, 2024). "Blockade of LepR in the DMH prevented the activation of BAT by leptin, implicating a role for this hypothalamic site in the sustained thermogenic effects of leptin during obesity." (PMID 36769012, 2023). "This information is relevant because, in subjects with obesity with leptin receptor resistance, the lack of signaling in bone cells and the reduction or inhibition of neuropeptide Y can contribute to deleterious effects on bones." (PMID 36831188, 2023). "A Mexican case-control study consisting of 100 participants with normal weight and 100 participants with obesity also found significant interactions between SFA intake and leptin receptor (LEPR) SNP rs1137101 on TC (Pinteraction = 0.002) and triglyceride (Pinteraction = 0.02) levels." (PMID 36776603, 2023). "Meanwhile, leptin-induced STAT3 phosphorylation was significantly impaired under Slc7a5 deficiency in LepR-expressing VMH neurons, but not in ARC neurons, prior to the onset of obesity." (PMID 36862514, 2023). "The highest prevalence of monogenic obesity was seen in a highly consanguineous population of Pakistan in a study of obese children that investigated only 3 monogenic obesity genes (LEP, LEPR, and MC4R) and found around 30% of the cases carried pathogenic variants." (PMID 37329217, 2023). "However, in ob/ob mice, which exhibit obesity due to the inactivation mutation of the leptin gene, metformin may not exert its leptin-sensitizing effects through promoting leptin receptor expression, resulting in minimal or negligible effects on body weight regulation." (PMID 37860765, 2023).
Obesity (continued). "In this study, we examined the hypothesis that genetic deletion of LepR in endothelial cells alters the metabolic phenotype of mice and actively contributes to the development of high-fat diet (HFD) diet-induced obesity." (PMID 37217565, 2023). "On the other hand, loss of LepR in POMC/CART, but not AgRP/NPY, neurons in the adult mice promotes obesity only when fed HFD These results suggest that the primary target of leptin is context-dependent." (PMID 37547309, 2023). "Since obesity is a key factor in T2DM development, it’s suggested that LEPR signaling may be involved in T2DM’s origin." (PMID 38198642, 2023). "We appreciate that heterozygous mutations in genes such as ALMS1, BBSs, LEPR, POMC, and PCSK1 have not been shown to be sufficient to cause the disease of obesity, except for the complete loss-of-function mutations of PCSK1, but not for POMC or LEPR mutations." (PMID 37835041, 2023). "Although all mice developed obesity in response to HFD, mean body weight changes and the percentage of weight gain over 16 weeks were significantly higher in End.LepR-KO mice compared to age-matched End.LepR-WT controls, in both male and female mice." (PMID 37217565, 2023). "Deletion of LepR gene specifically in AgRP/NPY, but not in POMC/CART, neurons in the adult mice (to avoid compensatory effects of gene deletion) causes obesity under a standard chow diet." (PMID 37547309, 2023). "Previous studies indicated that LEPROT could negatively regulate the cell surface expression of LEPR and the silencing LEPROT expression in the mouse hypothalamic arcuate nucleus prevented the development of high-fat-diet-induced obesity." (PMID 35223490, 2022). "Due to the homozygous leptin receptor deletion, db/db mice do not receive the satiety signal in the brain and become hyperphagic, resulting in the development of obesity and T2DM by 8 weeks of age." (PMID 36139465, 2022). "The role of leptin and the leptin receptor gene in human obesity is now emerging but not well understood." (PMID 36232301, 2022). "Zucker rats are a model of genetic obesity that have a non-functional leptin receptor, which leads to hyperphagia and, consequently, obesity." (PMID 35976296, 2022). "Protein tyrosine phosphatase 1B (PTP1B) is a negative regulator of insulin and leptin receptor sensitivity in multiple tissues through the dephosphorylation of IRS1 and JAK2, respectively, and is a major contributor to obesity precipitated resistance to these hormones in the brain." (PMID 36111295, 2022). "EREG/LepR regulated glucose uptake without changes in obesity in Lepob mice via mechanisms, including ERK activation and translocation of GLUT4 to the cell surface." (PMID 35159237, 2022). "Mice with two copies of the non-functional mutant leptin gene (ob/ob) or mutant leptin receptor gene (db/db) develop hyperphagia and obesity, despite consuming a normal chow diet." (PMID 36077188, 2022). "In leptin receptor deficient db/db mice, C57BL/KsJ-db/db nude (BKS-db/db) mice carry a mutation in the leptin receptor gene characterized by extreme obesity and early onset of hyperglycemia and hyperinsulinemia or normal insulinemia." (PMID 34673835, 2021). "Significant increases in body weight from baseline were observed until day 5 of treatment with either Allo-aca or control peptide, suggesting no exacerbation of obesity with the leptin receptor blockade." (PMID 34276408, 2021). "In these seven studies, no overall increased frequency of overweight or obesity in in LEPR wt/- vs wt/wt relatives was found." (PMID 34448070, 2021). "Second, although an alternative to genetic obesity is high fat diet-induced obesity, mice lacking all isoforms of the leptin receptor in myeloid cells, generated using Lyz2Cre mice, have already been studied in the context of high fat diet feeding." (PMID 34526546, 2021).